FAM170B (family with sequence similarity 170 member B)
Description:
Plays a role in fertilization through the acrosome reaction.
Synonyms: C10orf73; AC084727.4
Tractability: No criterion of Open Targets' tractability assessment is met for any kind of drug.
Gene: Protein-coding gene on chromosome 10 (49,131,154 to 49,134,021, reverse strand). Ensembl gene ENSG00000172538.
Subcellular location: Cytoplasmic vesicle, secretory vesicle, acrosome; Cytoplasmic vesicle, secretory vesicle, acrosome outer membrane
Gene Ontology:
Molecular function: protein binding
Biological process: fertilization; positive regulation of acrosome reaction; regulation of fertilization
Cellular component: acrosomal vesicle; outer acrosomal membrane
Genetic constraint (gnomAD): Loss-of-function variants: 6 observed, 6.1 expected, observed/expected ratio (o/e) 0.98, 90% interval 0.53 to 1.76. That is too few expected variants to judge how well the gene tolerates losing a copy. Missense variants: 417 observed, 377.05 expected, observed/expected ratio (o/e) 1.11, 90% interval 1.02 to 1.2. Synonymous variants: 163 observed, 154.82 expected, observed/expected ratio (o/e) 1.05, 90% interval 0.93 to 1.2.
Homologues: Orthologues: chimpanzee FAM170B (98% identical), pig FAM170B (70% identical), rat Fam170b (67% identical), mouse Fam170b (65% identical).